HSF1 (heat shock transcription factor 1)
Diseases named in the same sentence as HSF1 in open-access papers (continued):
Sharing a sentence is not in itself a finding about the gene and the disease.
cancer (continued). "HSF1 involvement in cancer is a highly discussed topic in the recent years and it is becoming clear that HSF1 supports tumor cell proliferation, survival, invasion and metastasis in a wide range of cancers." (PMID 34198675, 2021). "Many studies have described HSF1 overexpression in several types of cancer cells (e.g., breast, prostate, colorectal) although its expression does not always correlate with HSP expression." (PMID 33808130, 2021). "HSF1 protects cancer cells from apoptosis and induces drug resistance by stimulating the transcription of genes encoding HSPs." (PMID 34539881, 2021). "Intriguingly, using closed form ATP-bound HSP90 mutants that can be co-precipitated with HSF1, a known facilitator of cancer, we show that also endogenous HSF2 co-precipitates with HSP90." (PMID 34331200, 2021). "Of the HSPs, HSP70, is one of the best-characterised HSF1 targets, and is expressed at high levels in a variety of cancers." (PMID 33268814, 2021). "The dysregulation of HSF1 signaling has been observed in a wide range of cancers, and this dysregulation is regarded as a pivotal regulator of EMT and cancer stem-like traits." (PMID 33407730, 2021). "Our pan-cancer analysis provides a deep understanding of the functions of HSF1 in oncogenesis and metastasis in different cancers." (PMID 34239690, 2021). "Across multiomic signatures, the most striking enrichment involved overexpression of protein synthesis genes in HSF1-dependent cells of several cancer subsets." (PMID 33328249, 2021). "The characterization of HSF1 direct target genes in basal conditions and in response to acute stress, chronic protein misfolding diseases, or in cancer cells reveals cell-context-specific sets of HSF1-regulated genes, some of which contribute to pathogenesis." (PMID 33208463, 2021). "The present study systematically characterized the prevalence and prognostic value of HSF1 expression in pan-cancer." (PMID 34239690, 2021). "In advanced stages of other cancers, the expression and activation of HSF1 has been shown to be elevated." (PMID 34064083, 2021). "In many cancers cell lines, quercetin has targeted HSF1-dependent HSPs indicating antitumor activity." (PMID 34199460, 2021). "Meanwhile, various small-molecule inhibitors of HSF1 are currently being developed and tested in preclinical trials and considered as potential tools in the fight against cancer." (PMID 33806538, 2021). "Since its recognition as an HSF1 inhibitor, KRIBB11 has been reported to increase susceptibility to various anticancer molecules in different types of cancer cells in vitro." (PMID 34299435, 2021). "The present study revealed the relationship between HSF1 and tumor immune cells and investigated the immune status of cancer patients by examining the HSF1 expression." (PMID 34239690, 2021). "Under these stress conditions, HSF1 is elevated and activated, and thus, high HSF1 expression and activation is observed in various cancers." (PMID 34064083, 2021). "KRIBB11, an HSF1 inhibitor, was shown to sensitize various types of cancer cells to treatment with several anticancer drugs." (PMID 34299435, 2021). "Otherwise, the transcriptional program of HSF1 in cancer, beyond the expression of HSP genes, also involves the repression of genes encoding pro-apoptotic proteins such as XAF1, SMAC, BCL10 and BAX." (PMID 34198675, 2021). "Cancer cells often rely on protein degradation and folding pathways (i.e. proteasome, autophagy and HSF1 pathways) to survive the high proteotoxic stress levels associated with malignancy." (PMID 33268814, 2021). "The HSF1 expression exhibited strong correlations with immune checkpoint genes according to pan-cancer analysis." (PMID 34239690, 2021). "The correlation of the HSF1 expression with MSI was also investigated in 33 types of cancer, LUSC, PRAD, KIRC and STAD exhibited positive correlations, and READ and PCPG exhibited negative correlations." (PMID 34239690, 2021).
cancer (continued). "Since inhibition of HSF1 appears to be a promising therapeutic strategy for cancer treatment, the first attempts to develop a targeted inhibitor of HSF1 activity were made using natural compounds with pleiotropic activity (e.g., quercetin or triptolide)." (PMID 34200371, 2021). "Currently, HSF1 is recognized as a major player in several diseases including cancer and neurodegenerative disorders." (PMID 34198675, 2021). "Altogether, it seems that MA-induced HSF1-mediated cytoprotection can be a common mechanism that counteracts MA toxicity in various types of cancer cells." (PMID 34200371, 2021). "Particularly, it has been demonstrated that HSF1 regulation in various cancers is correlated with different processes, such as cell death, proliferation, and metastasis." (PMID 34064083, 2021). "Silencing HSF1 by RNA interference or inhibiting HSF1 by chemical inhibitors sensitizes cancer cells to chemotherapeutic reagents or hyperthermia therapy." (PMID 33675143, 2021). "Apart from its critical role in cancer initiation, increasing evidence suggests that cancer cells become reliant on HSF1 to maintain their malignant phenotypes." (PMID 33422093, 2021). "Numerous studies have shown the advantages of HSF1 inhibition in cancer by describing its anti-tumor effects." (PMID 33808130, 2021). "The methylation of HSF1 DNA was decreased in most cancers and negatively correlated with the HSF1 expression." (PMID 34239690, 2021). "In highly tumorigenic cells, HSF1 transcriptional activity regulates cancer-specific genes, which are different from genes activated during physiological processes." (PMID 34771616, 2021). "Increased HSF1 phosphorylation and decreased HSF1 methylation were observed in many types of cancer." (PMID 34239690, 2021). "More recently, the dysregulation of HSF1 and the crucial roles this stress-protective transcription factor plays in the pathophysiological contexts of both neurodegenerative disease and cancer have been of great interest." (PMID 33208463, 2021). "Together, our study provides insights into the application of HSF1 as a potential prognostic biomarker in several cancers in the context of immunooncology and contributes to the development of HSF1-targeting therapeutic strategies." (PMID 34239690, 2021). "To investigate the association between the HSF1 expression and clinicopathological features in multiple cancers, we assessed the HSF1 expression in stage I, II, III, and IV, cancer patients." (PMID 34239690, 2021). "We recently showed that cyclosporin A enhanced the sensitivity of cancer cells to hyperthermia and chemotherapy by promoting the phosphorylation of HSF1 at S303 and S307 and suppressing the expression of HSPs." (PMID 34239690, 2021). "Mentionable, tumor tissues have been referred to as a “chronic PTSs” to the organism and cancer cells seems to be more susceptible to proteomic perturbation compared to normal cells, which suggested the core role of HSF1 on sustain the malignancy of cancer." (PMID 33422093, 2021). "It has been shown that HSF1 can play a role in cancer promotion both indirectly via the regulation of HSPs and directly by regulating pro-tumoral gene expression." (PMID 33808130, 2021). "In cancer cells, HSF1 also broadly upregulates a large palette of tumor-promoting genes involved in cell cycle, DNA repair, metabolism, adhesion, and protein translation." (PMID 34188043, 2021). "MiR137 plays a role as a tumor suppressor in cancer; meanwhile, HSF1 can directly interact with its host gene MIR137HG to inhibit its expression and promote CRC occurrence." (PMID 33767996, 2021). "In cancer cells, HSF1 seems to promote epithelial–mesenchymal transition (EMT) either inducing the expression of N-cadherin and mesenchymal markers or downregulating the expression of E-cadherin and epithelial markers." (PMID 34198675, 2021).
cancer (continued). "Due to cytotoxic effects and thus stress-induced environments resulting from chemotherapies, which have been shown in other cancers to increase HSF1 and heat shock proteins, we further explored the effect of chemotherapy on antibodies targeting HSF1." (PMID 34439354, 2021). "The accumulating evidence in cancers for HSF1 activation suggests that it acts as a potent carcinogen in various cancers." (PMID 34064083, 2021). "Then we searched for the hypothetical influence of the HSF1 status on functions of ERα-related genes in actual cancer tissue." (PMID 34783649, 2021). "DYRK2 phosphorylates and activates both HSF1 and the 26S proteasome and thereby activates the proteotoxic stress pathway promoting tumorigenesis in cancers such as triple-negative breast cancer (TNBC) and multiple myeloma (MM)." (PMID 33376136, 2021). "This agrees with the established critical role that HSF1 plays in tumour initiation and in promoting and maintaining cancer cell proliferation." (PMID 33268814, 2021). "HSF1 plays an important role in the initiation, promotion and progression of different types of cancer." (PMID 34917120, 2021). "Understanding how HSF1 regulates gene repression is a crucial question, given the dysregulation of HSF1 target genes in both cancer and neurodegeneration." (PMID 33208463, 2021). "We also investigated the pan-cancer alterations of HSF1 using the cBioPortal (TCGA, Pan-Cancer Atlas) database." (PMID 34239690, 2021). "And there are reports that after HSF1 is activated, it can regulate the expression of Hsp70 and induce carboplatin resistance in cancer cells." (PMID 34539881, 2021). "Nevertheless, differences between ER+ and ER− cases were higher in the presence of high levels of HSF1, which implicates that HSF1 increases the disparity of the transcriptome of ER+ cancers." (PMID 34783649, 2021). "Collectively, these results indicate that the proliferation, invasion and cancer stem-like characteristics promoted by CAF-derived TSP-4 is achieved by activation of HSF1 signaling." (PMID 33407730, 2021). "We also examined the potential relationship between genetic alterations in HSF1 and the prognosis of patients with different types of cancer." (PMID 34239690, 2021). "HSF1 plays a role in stabilizing cancer proteome, and its silencing in cancer cells suppresses oncogenic proteins." (PMID 34064083, 2021). "Here, we identify pericentric heterochromatin of chromosome Y as a primary target of HSF1, and not only as a HSF1 secondary target, in both cancer and primary cell lines." (PMID 33547955, 2021). "The samples were then dichotomised into high and low levels groups for DYRK2 and HSF1 in relation to a cut-off, determined using a receiver operating characteristic (ROC) curve, with cancer death as an endpoint." (PMID 33268814, 2021). "HSF1 is strongly involved in tumorigenesis and tumor progression, and it can drive migration, invasion, and anchorage-independent growth of cancer cells." (PMID 34681001, 2021). "Our data show that DYRK2 activates the pro-survival HSF1 pathway providing a support mechanism and a survival advantage to cancer cells." (PMID 33268814, 2021). "Cantharidin and Cardenolide CL-43 have been shown to inhibit HSF1 transcriptional activity in cancer cells." (PMID 34064083, 2021). "It has long been accepted that the involvement of HSF1 in cancer is limited to its role in the stress response." (PMID 33808130, 2021). "In cancer cells, HSF1 is phosphorylated by polo-like kinase 1 (PLK1) at serine 216, causing it to sequester Cdc20." (PMID 34922589, 2021). "Remarkably, the phosphorylation of the S303, S307, and S363 residues on HSF1 was increased in some cancers." (PMID 34239690, 2021). "To closely estimate the association between the HSF1 expression and the TME in a pan-cancer dataset, we further investigated the relationships between the HSF1 expression and two major types of immune modulators." (PMID 34239690, 2021).
cancer (continued). "Knockdown of the heat shock factor 1 (HSF1) gene coupled with Hsp90 inhibition was shown to disrupt cancer cell proliferation in vitro and tumor growth in vivo." (PMID 33525518, 2021). "The high expression of HSF1 significantly correlated with a poor prognosis of several types of cancer." (PMID 34239690, 2021). "Studies have suggested that HSP90AA1, HSP90AB1 gene products, and their associated chaperon proteins (Aha1, Cdc37, p23, and Tpr2) as well as HSP90-dependent transcription factor HSF1 are overexpressed in a variety of cancers." (PMID 34109171, 2021). "The overexpression of FTO facilitated cancer progression by stabilizing heat shock transcription factor 1 (HSF1) in a YTHDF2-dependent way." (PMID 34804925, 2021). "The master regulator of the stress response heat shock factor 1 (HSF1) is overexpressed in multiple cancers, controlling the transcription of genes involved in cell proliferation, survival and energy metabolism." (PMID 33593922, 2021). "Accumulating studies have demonstrated that the activation of HSF1 in cancers facilitates oncogenesis." (PMID 34064083, 2021). "The HSF1 expression affected DSS in eight types of cancer, including CESC, HNSC, KIRP, MESO, PCPG, SARC, USC, and UVM." (PMID 34239690, 2021). "We wanted to confirm the efficacy of HSF1 inhibitors on cancer cells that have multiple resistance mechanisms." (PMID 34203709, 2021). "According to the results from the TIMER database, HSF1 exhibited inconsistent mRNA expression in 34 types of human common cancer." (PMID 34239690, 2021). "HSF1 inhibitors sensitize a wide variety of resistant cancer cells to drugs that induce ferroptosis." (PMID 34223704, 2021). "Santagate and colleagues reported that protein translation and HSF1 activation were coordinated to support anabolic metabolism in malignant cancer cells and that cephaeline is a translation inhibitor." (PMID 34203709, 2021). "Next we set to assess the role of HSF1-dependent matrix remodeling in supporting cancer cell proliferation." (PMID 33288768, 2020). "Several studies have also provided evidence to show that not only is HSF1 essential for transformation but is also hyperactivated and actively promotes enhanced metastatic and/or resistant properties within cancer cells." (PMID 32331382, 2020). "While beyond the scope of the present study, it would be interesting to examine the effect of fisetin treatment on the sumoylation of HSF1 in cancer cells." (PMID 32530958, 2020). "In cancer cells, HSF1 can drive a transcriptional program distinct from heat shock response to support malignant phenotypes." (PMID 32838807, 2020). "A key role in cancer was established when Hsf1 null mice were found to be extremely resistant to tumorigenesis." (PMID 33288768, 2020). "While bortezomib acts to trigger the heat shock response in some cancers, the Hsp70/co-chaperone system maintains HSF1 in an less active immature form." (PMID 32796891, 2020). "HSF1 is found to mediate the protection of cancer cells from programed cell death by overriding cell cycle checkpoints and thus exacerbating metastasis." (PMID 32457290, 2020). "With continued identification of the multifaceted ways in which HSF1 facilitates tumorigenesis, it has become an attractive target for cancer therapy." (PMID 32331382, 2020). "The stromal HSF1 program is completely different from the program HSF1 drives in the adjacent cancer cells or during heat-shock." (PMID 33288768, 2020). "Fisetin has been reported to impact other disease pathways, such as those mediated by HSF1, NF-kappaB and c-Jun/AP-1, each of which has established connections to both cancer and sumoylation." (PMID 32530958, 2020). "Hsf1 has been shown to promote tumorigenesis and cancer progression, and many tumor entities are addicted to high levels of molecular chaperones, like Hsp70, Hsp90, and Hsp27, and high levels of Hsp70 and Hsp90 have been associated with poor prognosis." (PMID 32490574, 2020).
cancer (continued). "Numerous studies have shown that human cancer cells exhibit high expression of HSF1, which supports tumorigenesis." (PMID 32408596, 2020). "In malignant cancer cell lines, HSF1 is reported to bind the gene promoters of multiple TRiC subunits." (PMID 32331382, 2020). "Heat shock factor 1 (HSF1) is a powerful multifaceted oncogenic modifier that plays a role in maintaining the protein balance of cancer cells under various stresses." (PMID 32110802, 2020). "The surface area covered by secreted collagen was reduced in Hsf1 null MEFs compared to WT counterparts, suggesting that stromal HSF1 is required for proper ECM assembly by cancer-conditioned fibroblasts." (PMID 33288768, 2020). "Key to the development of an HSF1 inhibitor suitable for clinical use is gaining a comprehensive understanding of the mechanistic basis for HSF1 activation in cancer." (PMID 32331382, 2020). "The majority of the available information related to HSP expression from both the stress response and cancer fields involves HSF1, and we have therefore concentrated on this principal transcription factor." (PMID 32331382, 2020). "This transcriptional program, called the HSF1 cancer signature (HSF1-CaSig) differs from that induced by heat shock, since a major portion of the genes are uniquely regulated in cancer." (PMID 32408596, 2020). "The up-regulation of HSF1 promotes the proliferation, migration, and invasion of cancer cells and can serve as a prognostic marker in cancer." (PMID 32943987, 2020). "HSF1 mRNA levels are frequently elevated across a larger percentage of cancer cases, as suggested by tumor biopsy analysis, although the biological processes that regulate HSF1 gene expression are yet to be fully determined." (PMID 32331382, 2020). "HSF1 can also mediate its effects upon the cancer transcriptome indirectly through the actions of the protein products of its target genes, for example, the RNA-binding protein HuR." (PMID 32331382, 2020). "The lncRNAs such as NEAT1, lincRNA‐ROR, EFNA3, and GAS5 are HSF1 targets, which are all involved in cancer." (PMID 32691951, 2020). "HSF1 has been previously linked to CAC, as its activation in cancer cells was shown to activate mTOR and increase glutaminolysis, thus promoting tumor growth." (PMID 33288768, 2020). "This intriguing finding is supported by earlier reports showing that Yy1, cMyc and Hsf1 orchestrate early developmental processes that cancer cells hijack during disease progression and metastasis." (PMID 32927726, 2020). "This phenomenon was initially attributed mainly to HSF1’s activity in cancer cells; however, a complementary crucial role for HSF1 was recently demonstrated in CAFs13,21." (PMID 33288768, 2020). "Together, these studies demonstrated that cancer cells are frequently dependent upon HSF1 to maintain the transformed state and to form tumors." (PMID 32331382, 2020). "Our mouse and human studies confirm that while HSF1 is activated in cancer cells, it is also activated in the stroma, mainly in fibroblasts but possibly also in other cell types in the TME." (PMID 33288768, 2020). "Through this function, Hsf1 is in metazoa at center stage of many physiological and pathophysiological processes like post‐embryonic development and aging, cancer, and neurodegeneration." (PMID 32490574, 2020). "In contrast, accumulating evidence revealed that HSF1 has multiple additional functions, including roles in autophagy, apoptosis, immune response, cell growth arrest, and even cancer development." (PMID 32943987, 2020). "In fibroblasts co-cultured with cancer cells HSF1 drives the expression of genes involved in adhesion and wound healing, leading to activation of genes involved in ECM organization in adjacent cancer cells." (PMID 33288768, 2020). "Recently, a meta-analysis of patient samples revealed that HSF1 is overexpressed in different types of cancers mainly due to amplification of the chromosome region 8q24.3, wherein the gene encoding HSF1 resides." (PMID 32408596, 2020).